CD47 (CD47 molecule)
Diseases named in the same sentence as CD47 in open-access papers (continued):
Sharing a sentence is not in itself a finding about the gene and the disease.
ovarian carcinoma (continued). "CD47 expression is predictive of disease stage and prognosis in patients with ovarian cancer, whilst one study identified ovarian tumours to express the highest level of CD24 of all cancer types analysed, with its expression inversely correlating with patient RFS." (PMID 35020853, 2022). "The overexpression of CD47 in ovarian cancer cell lines promotes cancer cell growth and motility." (PMID 36611344, 2022). "CD47 inhibits macrophage phagocytosis, which contributes to ovarian cancer progression." (PMID 36352420, 2022). "The distinct functional roles of CD47 in ovarian cancer might be due to inherent heterogeneity in ovarian cancer or the small amount of single cells collected using scRNA-seq data." (PMID 34966389, 2021). "Therefore, it is urgent to elucidate roles of CD47 in ovarian cancer and to illustrate its immune interactions in ovarian cancer microenvironment." (PMID 34966389, 2021). "However, there is limited research probing into the role of CD47 regarding immune infiltration in ovarian cancer." (PMID 34966389, 2021). "CD47 expression level in ovarian cancer was significantly higher than that of normal ovary tissue." (PMID 34966389, 2021). "We found CD47 highly expressed in many types of cancers, including ovarian cancer." (PMID 34966389, 2021). "These suggested that CD47 might affect ovarian cancer tumorigenesis and prognosis through regulating TME." (PMID 34966389, 2021). "Our results indicated that CD47 is closely correlated to ovarian cancer immune microenvironment and might induce ovarian cancer heterogeneity." (PMID 34966389, 2021). "Together we found strong evidence that CD47 might be used as a prognostic biomarker in ovarian cancer patients." (PMID 34966389, 2021). "Increased CD47 impression has been reported in ovarian cancer." (PMID 34966389, 2021). "KM plotter was used to show how CD47 affect the prognosis of ovarian cancer patients." (PMID 34966389, 2021). "However, in ovarian cancer, CD47 was positively correlated to metastasis, negatively correlated to invasion and DNA repair." (PMID 34966389, 2021). "Moreover, we investigated the correlation of CD47 expression with immune-infiltrating cells in ovarian cancer using TIMER database." (PMID 34966389, 2021). "To further clarify ovarian cancer microenvironment and how CD47 might affect ovarian cancer heterogeneity and prognosis, we investigated whether CD47 was related to immune infiltration." (PMID 34966389, 2021). "A revolutionary advancement in immune-oncology research, CAR-T cell treatments were applied in the CD47 blockade arena, with studies showing tumor killing against lung, ovarian and pancreatic cell lines, as well as the blocking of pancreatic and ovarian cancer xenograft growth in vivo." (PMID 34944850, 2021). "However, CD47 is negatively correlated with invasion (R=-0.58; P<0.001) and DNA repair (R=-0.28; P<0.05) in ovarian cancer; with differentiation (R=-0.19; P<0.01) in colorectal cancer (CRC)." (PMID 34966389, 2021). "Moreover, our results demonstrated that CD47 expression level was correlated with ovarian cancer immune infiltration level." (PMID 34966389, 2021). "Violin plot showed the same trend of CD47 expression in the ovarian cancer cell microenvironment." (PMID 34966389, 2021). "The data suggested CD47 to be a potential biomarker for predicting ovarian cancer prognosis." (PMID 34966389, 2021). "Furthermore, functional investigations revealed that the CD47 overexpression in ovarian cancer cells significantly promoted migration and invasion, and that CD47 induced epithelial-mesenchymal transition (EMT) through modulating E-cadherin and N-cadherin." (PMID 33015199, 2020). "CD47 was first discovered on ovarian cancer cells as an overexpressed cell surface marker." (PMID 35582455, 2020). "In gastric cancer, CD47 expression is an independent negative prognostic factor for gastric cancer, and in ovarian cancer, it is associated with adverse clinical characteristics and a poor prognosis." (PMID 30653520, 2019).
ovarian carcinoma (continued). "In addition, CD47 knockdown using shRNA in the SK-OV-3 ovarian cancer cell line promoted in vitro macrophage phagocytosis and inhibited tumor initiation in vivo, suggesting that such an anti-tumor effect is CD47 dependent." (PMID 28380460, 2017). "Adding anti-CD47 mAb therapy as a supplement to the standard therapeutic schemes may prevent ovarian cancer metastasis and recurrence." (PMID 28380460, 2017). "These primary ovarian cancer spheres were found to express both CD47 and the TICs marker CD133." (PMID 28380460, 2017). "Our results support an intrinsic role of CD47 in ovarian cancer progression and immune evasion." (PMID 28380460, 2017). "Thus, we suppressed CD47 expression in the SK-OV-3 ovarian cancer cell line using short-hairpin RNAs (shRNA) that target CD47 transcripts." (PMID 28380460, 2017). "CD47 expression is elevated in ovarian cancer and indicates poor prognosis." (PMID 28380460, 2017). "To test the killing activity in vitro, we tested CD47 CAR-T cells by RTCA assay (Real-time cytotoxicity assay) with CD47-positive cells expressing a high level of CD47 antigen: ovarian cancer cells, A1847, and SKOV-3 and with cancer cells expressing a low level of CD47: A549 cells and Hep3B cells." (PMID 29065481, 2017). "Thus, anti-human CD47 antibody-conjugated pSGNs can specifically target ovarian cancer cells and enable effective photothermal therapy with a reduced amount of gold nanoshells." (PMID 26318039, 2015). "In this study, CD47 was used because it has been identified as a tumor antigen of ovarian cancer." (PMID 26318039, 2015). "However, only a few studies have investigated the relationship between CD44, CD47 and c-met and ovarian cancer, particularly OCCC." (PMID 25658794, 2015). "Indeed, early studies showed that ovarian carcinoma cell lines express increased levels of CD47, the functional significance of which was unclear at that time." (PMID 23401787, 2013). "In the present work, transfection studies were undertaken with a human ovarian carcinoma cell line and a mouse lung fibroblast cell line, rather than human chondrocytes, in an attempt to provide additional understanding of CD47/IAP involvement in cellular mechanotransduction." (PMID 18186923, 2008). "Interestingly, these cells are known for their proliferation, recurrence, and resistance; hence, it has been suggested that anti-CD47 monoclonal antibodies may play a significant part in prevention and treatment of metastatic and recurrent ovarian cancer." (PMID 38892394, 2024). "Therefore, it can be speculated that high CD47 expression will promote immune escape of ovarian cancer." (PMID 38832992, 2024). "However, there are limited studies on the role of CD47 in immune invasion of ovarian cancer." (PMID 38832992, 2024). "They speculated that exosome CD47 may be a favorable therapeutic target for ovarian cancer." (PMID 38832992, 2024). "Moreover, CD47 expression influenced response to adjuvant chemotherapy in patients with ovarian cancer, and thus CD47 might serve as a predictive marker as well." (PMID 38493445, 2024). "In addition, CD47 was identified as OA3, an antigen overexpressed on ovarian carcinoma cells." (PMID 35884427, 2022). "Consequently, CD47 has been tested in ovarian cancer as a promising CAR-T cell-based therapy." (PMID 36352420, 2022). "Therefore, in this study, we aimed to clarify functional role of CD47 in ovarian cancer." (PMID 34966389, 2021). "Therefore, CD47 high expression might contribute to immune escape, leading to worse prognosis of ovarian cancer." (PMID 34966389, 2021). "However, how CD47 might be correlated with ovarian cancer immune microenvironment and lead to tumor heterogeneity has not been fully studied." (PMID 34966389, 2021). "Therefore, CD47 may be used as a candidate prognostic biomarker and provide us with new insights into potential immunotherapy in ovarian cancer patients." (PMID 34966389, 2021).
ovarian carcinoma (continued). "Therefore, in this study, we genetically manipulated an oncolytic adenovirus designated SG635‐SF to express an engineered SIRPα and IgG1 Fc fusion protein and investigated its therapeutic effect against CD47‐high‐expressing ovarian cancer cells both in vitro and in vivo." (PMID 31899582, 2020). "Both CD47 and CD24 are overexpressed in various cancers, including ovarian cancer, where they deliver “don’t eat me” signals to macrophages, preventing the immune system from effectively eliminating tumor cells." (PMID 40330466, 2025). "In ovarian cancer models, PPAB001 has shown enhanced efficacy compared to therapies that block only CD47 or CD24 individually." (PMID 40330466, 2025). "Strong antitumour activity has also been observed in anti-HER2 and anti-CD47 THP-1 human macrophages towards HER2+ SKOV3 and CD47+ A2780 human ovarian cancer cells." (PMID 40574837, 2025). "Potent synergy by blocking CD47/SIRPα and CD24/Siglec-10 pathways, enhances macrophage phagocytosis and anti-tumor immune responses; reduces tumor growth in ovarian cancer models." (PMID 40330466, 2025). "In the ovarian carcinoma cell line OV10, Vn-bead binding was CD47- and integrin-dependent and correlated with both integrin αv and CD47 expression, and the CD47 IgV domain alone was sufficient." (PMID 38426113, 2024). "In September 2023, the team of Tu Jiajie, Institute of Clinical Pharmacology, Anhui Medical University, constructed HER2-targeting CAR-Ms and CD47-targeting CAR-Ms, and co-cultured them with antigen-positive ovarian cancer cells in vitro." (PMID 39421021, 2024). "In an unrecruited trial, the immune checkpoint inhibitor pembrolizumab, CD47 inhibitor ALX148, and liposomal doxorubicin were evaluated for safety and efficacy in patients with recurrent platinum-resistant ovarian cancer (NCT05467670)." (PMID 38832992, 2024). "Considering the therapeutic relevance of targeting the CD47/TSP-1 axis, we used the CD47-derived TAX2 peptide to selectively antagonize it in a preclinical model of aggressive ovarian carcinoma." (PMID 39138571, 2024). "CD47 is overexpressed in a variety of tumors, and we only performed PET/CT imaging with [68Ga]Ga-NOTA-C2 in 3 models of colon cancer, ovarian cancer, and gastric cancer." (PMID 36939440, 2023). "In summary, our study sheds light on the potential of anti-CD47 therapy as a potential approach to overcoming immunotherapy resistance and improving responses to PARP inhibitors in ovarian cancer." (PMID 37468567, 2023). "Then we showed that anti-CD47 therapy combined with olaparib also upregulated STING pathway markers (TBK1 and IFNB) in monocytes cocultured with ovarian cancer cells." (PMID 37468567, 2023). "Flow cytometry showed that two ovarian cancer cell lines SKOV3 and A2780 expressed high and low HER2, respectively, while CD47 was highly expressed in both cell lines." (PMID 37740183, 2023). "We noted that Olaparib significantly up-regulated CD47 and CCL2 expression in ovarian cancer cells in-vitro." (PMID 37468567, 2023). "Combined anti-CD47 therapy with olaparib also reduced cytokine secretion of IL6, IL18 and CCL2 from ovarian cancer cells." (PMID 37468567, 2023). "In vitro, dual blockade of CD47 and CD24 exhibited an additive effect on ovarian cancer cell phagocytosis." (PMID 35020853, 2022). "Our approach using the engineered monocytes can hence be readily extended to different types of cancers where CD47 is highly expressed, including acute leukemia, NHL, colorectal, and ovarian cancers." (PMID 35600645, 2022). "No recurrent MET fusions were identified, some of the fusion partners included HLA-DRB1-MET (lung cancer), CD47 (lung cancer), CAPZA2 (gastric cancer), AKAP9 (hepatobiliary cancer), CLIP2 (hepatobiliary cancer), and SLC25A19 (ovarian cancer)." (PMID 36369474, 2022). "CD47 mRNA level correlated with overall survival (OS) and progression-free survival (PFS) in ovarian cancer patients." (PMID 34966389, 2021).
ovarian carcinoma (continued). "CD47 was highly expressed in bladder urothelial carcinoma (BLCA), BRCA, CESC, cholangiocarcinoma (CHOL), colon adenocarcinoma (COAD) and ovarian cancer." (PMID 34966389, 2021). "Therefore, CD47 might play vital roles in affecting immune infiltration in ovarian cancer microenvironment and be used as a potential target in reversing immune escape and provide insights into understanding the function of CD47 in ovarian cancer prognosis and tumor immunology." (PMID 34966389, 2021). "Therefore, cancer therapies targeting CD47 might be used to treat ovarian cancer." (PMID 34966389, 2021). "Some cancer cells insensitive to CD47 signal blocking turned out to be sensitive to CD24 blocking, such as ovarian cancer." (PMID 33597922, 2020). "The SF fusion protein was effectively detected, and CD47 was successfully blocked in SK‐OV3 and HO8910 ovarian cancer cells expressing high levels of CD47." (PMID 31899582, 2020). "We first examined the CD47 expression levels in the CD133+ and CD133− sub-populations in five different epithelial ovarian cancer cell lines." (PMID 28380460, 2017). "Thus, CD47 antibody therapy may be a promising strategy to treat ovarian cancer." (PMID 28380460, 2017). "Similar to CD47 and PD-L1, the anti-phagocytic surface protein CD24 in ovarian cancer cells acts as the primary innate immune checkpoint, binding to the inhibitory receptor siglec-10 on TAMs’ surfaces to send out a “don't eat me” signal, thereby helping cancer cells escape from the immunity." (PMID 39003350, 2024). "The results showed that HER2 CAR-Ms and CD47 CAR-Ms significantly inhibited tumorigenicity and tumor proliferation of ovarian cancer cell lines, confirming CAR-mediated phagocytosis of macrophages on ovarian cancer cells." (PMID 39421021, 2024). "A treatment that combines engineered CAR-T cells targeting CD47 and inhibits secreted THBS2/THBS3 using antibodies may constitute a valuable therapeutic strategy to inhibit ovarian cancer progression." (PMID 36352420, 2022). "In addition, increased expression of checkpoint inhibitors such as PD-L1, CD47, CD73, in chemo naïve ovarian cancer cells and chemotherapy treated ovarian cancer cells have been noted." (PMID 36463238, 2022). "CD47 activates EMT through modulating E-cadherin and N-cadherin in ovarian carcinoma." (PMID 36429098, 2022). "In summary, our study showed that increased levels of CD47 could impact the ovarian cancer TME, indicating that CD47 might be used as a potential predictor of ovarian cancer heterogeneity." (PMID 34966389, 2021). "Although TIMER only investigated CD47 expression in 303 ovarian tumor samples but not in adjacent normal tissues, CD47 expression level in ovarian cancer was relatively high." (PMID 34966389, 2021). "CD47 expression was positively correlated with monocyte and TAM infiltration in ovarian cancer." (PMID 34966389, 2021). "CD47 expression was upregulated and connected to worse OS and PFS in ovarian cancer." (PMID 34966389, 2021). "Higher CD47 expression was connected to poorer OS and PFS in ovarian cancer." (PMID 34966389, 2021). "Since the efficacy of the promoter in a plasmid is critical for the expression of target sequences and varies according to cell type, we used a luciferase reporter system to test the efficacy of a panel of promoters in CD47‐high‐expressing SK‐OV3 and HO8910 ovarian cancer cells." (PMID 31899582, 2020). "We confirmed that CD47 is positive in the ovarian cancer cell lines SK‐OV3 and HO8910, while it is almost negative in HepG2 cell line." (PMID 31899582, 2020). "In conclusion, our results indicate that CD47 inhibits macrophage phagocytosis of ovarian cancer cells, and down-regulation of CD47 or inhibiting CD47 by mAb was able to reverse the negative effect." (PMID 28380460, 2017).
ovarian carcinoma (continued). "The pSGNs were first conjugated to anti-human CD47 antibodies (hCD47-pSGNs); the conjugated pSGNs recognized CD47 molecules expressed on the surface of human ovarian cancer cells TOV21G but not on mouse ovarian cells ID8." (PMID 26318039, 2015). "CD44, CD47 and c-met may have synergistic effects on the development of OCCC and are prognostic factors for ovarian cancer." (PMID 25658794, 2015). "It is the first time to prove that CD47 CAR-M could efficiently suppress the CD47hi ovarian cancer cells-formed tumor, which is worth further investigation for its potential application of CD47hi ovarian cancer." (PMID 37740183, 2023). "Similarly, and despite smaller size, a trend toward lower CD47 expression was seen among ovarian cancer patients who responded to ICI compared to those who did not respond (p = 0.09)." (PMID 37468567, 2023). "ALX‐148 specifically blocks the cd47 receptor, and since CD47/SIRPα axis additionally constrains the efficacy of tumour‐opsonising antibodies, a combination therapy pf ALX‐148 and other anticancer drug could boost their effect in platinum‐resistant ovarian cancer." (PMID 38450975, 2024). "(2021) reported delayed tumor growth in low STn expressing tumors when treated with the dual STn- and CD47-specific CAR-T cells, but not after therapy with the single anti-STn CAR-T cells in an in vivo ovarian cancer model." (PMID 37854601, 2023). "Unresectable/metastatic solid tumours (including ovarian cancer).SHR2150 (TLR7 agonist) and chemotherapy plus anti-PD1 mAb or anti-CD47 mAb (specific mAb identities not provided).Non-randomised, open-label." (PMID 35020853, 2022). "However, how CD47 might affect TME heterogeneity of ovarian cancer has not been fully investigated." (PMID 34966389, 2021). "Human ovarian cancer cell TOV21G expressing human CD47 on the cell surface and mouse ovarian cancer cell ID8 not expressing human CD47 was used as tumor models." (PMID 26318039, 2015). "Pre-clinically, neutralising anti-CD47 and anti-CD24 mAbs have demonstrated enhancement of non-specific macrophage phagocytosis of ovarian cancer cells in vitro, as well as inhibition of tumour growth in murine ovarian cancer models." (PMID 35020853, 2022).